CAPRIN2 (caprin family member 2)
Description:
Promotes phosphorylation of the Wnt coreceptor LRP6, leading to increased activity of the canonical Wnt signaling pathway. Facilitates constitutive LRP6 phosphorylation by CDK14/CCNY during G2/M stage of the cell cycle, which may potentiate cells for Wnt signaling. May regulate the transport and translation of mRNAs, modulating for instance the expression of proteins involved in synaptic plasticity in neurons (By similarity). Involved in regulation of growth as erythroblasts shift from a highly proliferative state towards their terminal phase of differentiation. May be involved in apoptosis.
Synonyms: C1QDC1; EEG1; RNG140; FLJ22569; FLJ11391; caprin-2; EEG-1
Tractability: Antibody: UniProt places it where antibodies can reach, with high confidence; its Gene Ontology location is reachable by antibodies, with medium confidence.
Gene: Protein-coding gene on chromosome 12 (30,709,512 to 30,823,302, reverse strand). Ensembl gene ENSG00000110888.
Subcellular location: Cytoplasm (Isoform 1); Mitochondrion (Isoform 2); Cytoplasm; Mitochondrion (Isoform 5); Cell membrane
Subcellular location (Human Protein Atlas): Cytosol; Centrosome; Nucleoplasm
Gene Ontology:
Molecular function: protein binding; signaling receptor binding
Biological process: negative regulation of cell growth; positive regulation of canonical Wnt signaling pathway; positive regulation of transcription by RNA polymerase II; dorsal/ventral axis specification; positive regulation of dendrite morphogenesis; positive regulation of dendritic spine morphogenesis
Cellular component: cytoplasm; cytosol; mitochondrion; receptor complex; plasma membrane
Genetic constraint (gnomAD): Loss-of-function variants: 42 observed, 93.73 expected, observed/expected ratio (o/e) 0.45, 90% interval 0.35 to 0.58. The upper end of that interval is the gene's LOEUF score, 0.58, which puts it in group 2 of 6, group 1 being the genes least tolerant of losing a copy. Missense variants: 957 observed, 1,054.2 expected, observed/expected ratio (o/e) 0.91, 90% interval 0.86 to 0.96. Synonymous variants: 392 observed, 377.86 expected, observed/expected ratio (o/e) 1.04, 90% interval 0.95 to 1.13.
Homologues: Orthologues: macaque CAPRIN2 (99% identical), chimpanzee CAPRIN2 (95% identical), pig CAPRIN2 (89% identical), guinea pig CAPRIN2 (88% identical), rabbit CAPRIN2 (85% identical), rat Caprin2 (81% identical), mouse Caprin2 (80% identical), tropical clawed frog caprin2 (49% identical), zebrafish caprin2 (37% identical), Drosophila melanogaster Capr (18% identical). Paralogues in human: CAPRIN1 (24% identical).
Diseases named in the same sentence as CAPRIN2 in open-access papers:
CAPRIN2 is named in the same sentence as 11 diseases in open-access papers, as found by Europe PMC text mining. Sharing a sentence is not in itself a finding about the gene and the disease. The quoted sentences say what the papers report.
hepatoblastoma (2 papers, 2021 to 2022). Hepatoblastoma (HB) is a malignant hepatic tumor and is the most common pediatric liver cancer. "CAPRIN2 R968/S969C, a gain-of-function mutation, actively regulated nuclear accumulation of β-catenin and promoted hepatoblastoma cell proliferation." (PMID 34511033, 2021).
breast carcinoma (1 paper, 2025). "However, higher expression of SH3RF1 is related to increased “stemness” properties of breast cancer cells and CAPRIN2 may also play a role in carcinogenesis." (PMID 40837030, 2025).
glioma (1 paper, 2021). A benign or malignant brain and spinal cord tumor that arises from glial cells (astrocytes, oligodendrocytes, ependymal cells). "Our results suggest that apart from regulating Caprin2 expression, lncRNA-MUF modulates the expression of several genes involved in the TGF-β pathway in glioma cells (vimentin, CTGF, c-Myc, and Snail1) with Snail1 as one of the primary targets." (PMID 35223453, 2021).
tumor (3 papers, 2020 to 2022). "Our data demonstrated that CDKN2B-AS1 could promote CRC cell proliferation and migration and facilitate CRC tumor growth through the miR-378b/cytoplasmic activation/proliferation-associated protein 2 (CAPRIN2) axis." (PMID 34511033, 2021). "This is the first time that CAPRIN2 has been reported to play a role in promoting tumor metastasis at the stage of ECM detachment." (PMID 36276162, 2022). "Our study showed that CAPRIN2 can inhibit ferroptosis of ECM detached tumor cells and promote cell survival." (PMID 36276162, 2022). "We found that CDKN2B-AS1 shRNA notably decreased CDKN2B-AS1 expression in tumor tissues, accompanied by an increase of miR-378b and a decrease of CAPRIN2." (PMID 34511033, 2021). "Downregulation of CDKN2B-AS1 suppressed tumor growth and Ki-67 staining in vivo that was related to the miR-378b/CAPRIN2 pathway." (PMID 34511033, 2021). "RT‐qPCR showed that CAPRIN2 was also significantly up‐regulated in tumour tissues than its paired normal tissues." (PMID 32691935, 2020). "Correlation analysis demonstrated that LINC00941 was positively correlated with CAPRIN2 expression in patient tumour tissues." (PMID 32691935, 2020). "At present, it is not clear whether CAPRIN2 is also regulated by LINC00941 in NPC and whether the LINC00941/CAPRIN2 axis is involved in regulating ferroptosis and metastasis of tumor cells." (PMID 36276162, 2022). "The results revealed that there were significant correlations between CAPRIN2 expression and clinicopathologic characteristics, including tumor-node-metastasis (TNM) stage, tumor invasion depth, node metastasis, and distant metastasis." (PMID 36276162, 2022). "It has been reported that CAPRIN2 is activated by LINC00941 through DNA looping in OSCC, which is involved in promoting cell proliferation and tumor formation." (PMID 36276162, 2022). "Moreover, the functions of CAPRIN2 in tumor ferroptosis have not been reported." (PMID 36276162, 2022).
cancer (1 paper, 2024). A tumor composed of atypical neoplastic, often pleomorphic cells that invade other tissues. "Furthermore, the observed association of CAPRIN2 with cell cycle processes suggests a potential impact on cancer cell proliferation." (PMID 39492622, 2024).
CAPRIN2 also shares sentences with these, for which no sentence is quoted: colorectal cancer (2 papers); latent infection (1); myocardial infarction (1); nasopharyngeal carcinoma (1); oral squamous cell carcinoma (1); prostate carcinoma (1).